BECN1 (beclin 1)
Diseases named in the same sentence as BECN1 in open-access papers (continued):
Sharing a sentence is not in itself a finding about the gene and the disease.
tumor (continued). "Extensive overexpression of Beclin 1 was significantly linked with histological markers of tumour aggressiveness, such as nodal involvement, high histological grade and vascular invasion." (PMID 20842118, 2010). "Beclin‐1 gene is a specific autophagy‐related gene, and the Beclin‐1 protein encoded by it is considered to be a tumor suppressor protein, which is able to regulate autophagy process, participate in the nucleation stage, and induce the aggregation of autophagy‐associated proteins." (PMID 39803233, 2025). "The proliferation of BAP1-deficient cells depends on the status of BECN1 tyrosine phosphorylation, which may contribute to tumor progression in certain cancer types." (PMID 40754831, 2025). "Loss of Beclin‐1 reduces basal autophagy and may exert a tumor‐suppressive effect during early tumorigenesis." (PMID 41329030, 2025). "The downregulation of Beclin‐1 has been linked to the environmental adaptation of cancer cells, allowing them to reprogram glucose metabolism and proliferate; however, it can also be upregulated depending on tumor type." (PMID 40529859, 2025). "This suggests that autophagy induced by BECN1 may play a crucial role in removing invasive microorganisms such as F. nucleatum from the tumor microenvironment, thereby reducing the risk of colorectal carcinogenesis." (PMID 40520902, 2025). "Additionally, in both laboratory and live settings, LS174T xenografted tumors containing a mutated caspase 8 cleavage site of Beclin-1 showed significant resistance to the anti-tumor effects of the combined treatment." (PMID 39650649, 2024). "Moreover, it has been reported that higher levels of Beclin-1 are associated with high-grade tumours, deep myometrial invasion and a poor five-year survival." (PMID 39596186, 2024). "To evaluate whether BECN1/YAP/TAZ (BYT)-deficient adipocytes could impact tumor growth, we generated doxycycline-inducible BYT KO adipocytes and performed a colony formation assay." (PMID 38744820, 2024). "Previous studies have demonstrated that, in UM patients, there is a frequent overexpression of autophagy-related proteins, such as MAP1LC3A (microtubule-associated protein 1 light chain 3 alpha) and BECN1 (beclin 1), which are associated with tumor progression and poorer outcomes." (PMID 38920653, 2024). "Nevertheless, it is becoming gradually clear that the loss of autophagy-related genes such as Beclin-1 can promote the earliest stage of tumor formation, and that upregulated autophagy can also assist tumorigenesis in dealing with various stresses such as hypoxia or immune attack." (PMID 37108476, 2023). "The authors illustrated that Beclin 1 loss promotes tumor development." (PMID 38069199, 2023). "Interestingly, levels of Beclin-1 have been investigated as an independently predicted marker of HCC tumor progression, significantly associated with disease-free survival and overall survival rates." (PMID 35159028, 2022). "The BECN1 protein expression was negatively associated with tumor size and differentiation." (PMID 36295086, 2022). "The loss of BECN1 weakened the tumor-promoting effect of FIRRE in CRC." (PMID 35110535, 2022). "Together with the previous works, our data support the notion that accelerated RNA splicing events in tumors can generate cancer-specific variants, and that variable expression of BECN1 isoforms can be found in different tumor cells and need to be investigated." (PMID 36008963, 2022). "Furthermore, the delayed tumor development in Atm-null mice associated with Beclin-1 heterozygosity that was correlated with the rescue of mitochondrial defects, not the rescue of DDR abnormalities." (PMID 35453338, 2022). "In addition, beclin 1 is a tumor-suppressor gene that can cause the induction of autophagy and inhibition of tumorigenesis." (PMID 35887232, 2022).
tumor (continued). "Moreover, various proteins associated with autophagy that directly suppress tumour development include Beclin-1, UVRAG, and Bif-1, as well as components that destroy proteins associated with tumour growth such as p62/SQSTM1." (PMID 34445354, 2021). "The underlying mechanism for the differing prognostic impact of Beclin 1 expression may depend on the intrinsic properties of the tumor subtype and the treatment regimen." (PMID 34559451, 2021). "Furthermore, autophagy-defective Beclin-1 mice and Atg-4C deficient mice are predisposed to tumor growth." (PMID 34201882, 2021). "Accordingly, it is reasonable to take on that increased Beclin-1 expression in OSCCs may be associated with disease progression; it can also contribute to greater tumour infiltration through the still unclear role of autophagy during the development of cancer." (PMID 34769649, 2021). "Consistently with our study, they also demonstrated the increase in Beclin 1 could cause long-term survival, which implied BECN1 was a tumor suppressor gene and may act as a prognostic biomarker." (PMID 32998713, 2020). "In vivo experiments in MCF-7 cells demonstrated that acetylation at these two sites is required for tumorigenesis, since MCF-7 cells overexpressing Beclin 1 K430/437R mutation inhibit tumor growth to a larger extent than cells overexpressing Beclin 1 wild-type do." (PMID 31877888, 2019). "However, Beclin-1 is an essential modifier of the autophagic process and has been implicated in tumor development." (PMID 30893939, 2019). "Notably, Beclin 1 was the first tumor suppressor demonstrated to be controlled by K11-linked poly-ubiquitination." (PMID 31787758, 2019). "By inducing autophagy, the associated Beclin-1 and LC-3 genes can suppress tumour growth." (PMID 30001631, 2018). "Reduced expression of Beclin-1 inhibits autophagy, which may induce tumor formation by causing oxidative stress, DNA damage or genomic instability." (PMID 30344951, 2018). "Indeed, loss of Atg5, Atg6/Beclin-1, or Atg12 compromised tumor and influenza A virus-infected cells to donate antigens for efficient cross-presentation." (PMID 25972871, 2015). "Allelic loss of the beclin 1 inhibited tumor formation in certain genotypes of mice." (PMID 26506105, 2015). "Additionally, Beclin-1 was proposed as a marker of HCC progression as co-expression of related genes was linked to HCC tumor progression." (PMID 26561802, 2015). "Further studies are required to delineate the functions of BECN1 and its potential correlation with NF-κBp65; this may promote a better understanding of the underlying mechanisms of carcinogenesis and tumor progression in HCC." (PMID 23833647, 2013). "Beclin 1, the first identified mammalian autophagy gene product, has been mapped to a tumor-susceptibility locus on chromosome 17q21 and is a haploinsufficient tumor suppressor that was originally isolated as a Bcl-2-interacting protein." (PMID 23573264, 2013). "Two study groups have generated BECN1-deficient mice to investigate whether BECN1 acts as a tumor suppressor, and whether loss of BECN1 may contribute to an increased cancer incidence." (PMID 23833647, 2013). "The underlying mechanism(s) of Beclin 1 to suppress tumorigenesis and tumor progression might be attributed to its multi-functions." (PMID 24260370, 2013). "In addition, low-expressed Beclin 1 was closely linked to tumor poorer differentiation, later pT stage, lymph node metastasis, distant metastasis and advanced FIGO stage (P<0.05)." (PMID 23573264, 2013). "Furthermore, we found that there was a similar significant association between decreased BECN1 mRNA levels and tumor grade." (PMID 21455500, 2011). "Indeed, our in ovo data confirmed this hypothesis in BAP1-deficient ccRCC cells treated with the Tat-BECN1 peptide, as tumor growth was significantly compromised compared to the Tat-scrambled peptide control." (PMID 40754831, 2025).
tumor (continued). "Similarly, silencing autophagic-associated protein Beclin-1 could inhibit autophagy and protect cells against death, contributing to tumor growth." (PMID 38402166, 2024). "The hypothesis of autophagic induction as oncosuppressive is underscored by critical genetic experiments demonstrating an increase in tumor burden and progression, following the heterozygous deletion of Becn1, which encodes Beclin 1, a core autophagic component." (PMID 35159071, 2022). "Beclin-1 gene monoallelic loss on chromosome 17q21, has been reported in 40–75% of human ovary, breast and prostate tumors, suggesting that autophagy may play the role of a tumor suppressor." (PMID 33297472, 2020). "Beclin 1, a tumor suppressor that interacts with Bcl-2, Bax, BAK, Casp8, and Bcl-XL, and triggers apoptosis and induces autophagy, was significantly increased in 60H muscle compared to that in age-matched wild-type mice." (PMID 41507123, 2026). "The expression levels of Beclin-1 were significantly elevated in certain treatment groups within the tumor microenvironment (TME)." (PMID 41550506, 2026). "BCc1 exhibits a dual regulatory effect—upregulating tumor-suppressive Beclin-1 while downregulating pro-survival ATG-4B, ATG-7, and mTOR—in a manner dependent on dose and administration route." (PMID 41550506, 2026). "It is revealed that Beclin-1-dependent autophagy restricted malignant progression by promoting tumor cell death." (PMID 41209546, 2025). "PIC can inhibit the phosphorylation activity of Beclin-1 and hinder its binding with Bcl-2, further triggering Beclin-1-dependent autophagic signaling activation, effectively suppressing tumor progression in GC xenograft models and inducing cell apoptosis." (PMID 40066330, 2025). "The earlier evidence came from studies on hemizygous mouse models for Beclin-1, which are prone to tumor development." (PMID 40444035, 2025). "In contrast, administration of the RPS6KA2 overexpression plasmid together with cisplatin reduced the expression of ATG5, ATG7, and BECN1 and inhibited tumor expansion." (PMID 41502518, 2025). "In cancer cell lines and mouse models, the absence of BECN1 has been shown to decrease autophagy and increase cell proliferation, providing evidence that BECN1 is a tumor suppressor gene." (PMID 40248706, 2025). "There is a strong connection between BECN1-mediated autophagy and the hypoxic conditions commonly present in the tumor microenvironment (TME), which in turn contributes to resistance against broad-spectrum anticancer drugs, such as bevacizumab." (PMID 39859167, 2025). "Beclin-1 represents one of the key regulators of autophagy that has been identified as a potential target in attempts to enhance the tumor sensitivity to treatment through the induction of autophagic cell death." (PMID 40403026, 2025). "This reduction suggests a tumor‐suppressor function, as high Beclin‐1 levels promote autophagy and reduce apoptosis." (PMID 40452796, 2025). "Our study illustrates that combining Everolimus with NDV and Beclin-1, which not only inhibits mTOR but also enhances autophagy, leading to increased tumor cell death." (PMID 40403026, 2025). "Conversely, numerous studies have demonstrated that elevated expression levels of ATG4B, ATG5, and Beclin‐1 in tumor tissues correlate with poor pathological outcomes in cancer patients." (PMID 40883962, 2025). "In breast cancer, high autophagic flux induces Beclin-1-dependent death, demonstrating its tumor-suppressive role." (PMID 40868135, 2025). "Among these, IL-6 has been associated with poor chemotherapy response, in part by regulating autophagy and promoting BECN1 phosphorylation, which strengthens tumor survival under treatment stress." (PMID 41155372, 2025).
tumor (continued). "PI3K/AKT activation has been shown to promote tumor-enhancing autophagy and to facilitate oncogenesis by repressing or functionally impairing key autophagy mediators such as Beclin-1, LC3, and p62." (PMID 41573680, 2025). "This study shows that the binding of Bif-1 to UVRAG-Beclin-1 complex has significant potential as a potential activator of phagocytosis and tumor suppressor." (PMID 40688079, 2025). "Because these two processes are tightly correlated and because their crosstalk is heavily shaped by the Bcl-2:beclin-1 complex, therapeutic reprogramming aims to reshape this balance in a direction that disadvantages tumour survival." (PMID 41511337, 2025). "Treatment with an autophagy-inducing peptide, Tat-BECN1, overcomes the tumor growth and inhibitory effect on autophagy of deregulated receptor tyrosine kinases, such as HER2/ERBB2." (PMID 40754831, 2025). "NDV causes oncolysis and activates the immune system, Everolimus hinders tumor cell proliferation by focusing on the mTOR pathway, and Beclin-1 regulates autophagy to enhance tumor cell death." (PMID 40403026, 2025). "Frequent allelic deletions of Beclin-1—ranging from 40% to 75%—have been identified in prostate, ovarian, and breast cancers, underscoring its role as a tumor suppressor gene." (PMID 40001518, 2025). "As expected, the OE upregulated the expression of LC3 and Beclin-1 and significantly counteracted the inhibitory effect on tumor cell survival." (PMID 39753527, 2025). "This functional domain, which activates VPS34, is likely integral to Beclin-1’s tumor-suppressive properties." (PMID 40001518, 2025). "Early research on the Becn1 gene in mice revealed that the whole-body hemizygosity of Becn1 resulted in tumor initiation in the liver, lymphatic tissues, and lungs, while no such effects were observed in other tissues." (PMID 40723786, 2025). "Certain signaling mediators, such as mTORC1, TP73, and Beclin‐1, are crucial for the proper tumor suppressive activity of DEPDC2." (PMID 39971705, 2025). "One study used a CRISPR screen to find genes which, when lost, abrogate the tumour suppressive function of Beclin 1 in order to understand how Beclin 1 inhibits cell proliferation." (PMID 40650785, 2025). "Specifically, they showed that Beclin 1 promotes E-cadherin localisation to the plasma membrane, restricting tumour growth and metastasis." (PMID 40650785, 2025). "These approaches are expected to further contextualize the molecular insights regarding the HMGB1/ZNF460/BECN1 axis within the broader “tumor ecosystem” framework, thereby offering a more comprehensive strategy to address radiotherapy resistance in CRC." (PMID 41164196, 2025). "In breast cancer, abnormal methylation of BECLIN-1, an autophagy-related gene that acts as a tumor suppressor, can be considered as a mechanism of autophagy prevention and induction of tumor." (PMID 40949798, 2025). "BECN1, the first tumor-associated autophagy-related gene (ATG) identified in mammals, is mono-allelically deleted in BC and functions as a tumor suppressor." (PMID 40659605, 2025). "Compared with normal samples, tumor samples have lower BECN1 expression levels, which has been reported to contribute to cancer pathogenesis and progression." (PMID 40659605, 2025). "In particular, among the various autophagy-related genes, the function of Beclin-1 has been demonstrated to induce spontaneous tumor formation." (PMID 41294748, 2025). "When Beclin-1 is knocked out, tumor cells acquire EMT mesenchymal characteristics by stabilizing the mRNA level of ZEB1." (PMID 40229278, 2025). "The reduced form of HMGB1 binds to the RAGE and induces Beclin-1-dependent autophagy, promoting tumor cell resistance to diverse chemotherapeutic agents including alkylators, tubulin disruptors, and DNA intercalators." (PMID 41465435, 2025).
tumor (continued). "In vivo, co-administration of the sh-RPS6KA2 plasmid and cisplatin significantly increased the expression of ATG5, ATG7, and BECN1, as well as promoted subcutaneous tumor growth compared to cisplatin monotherapy." (PMID 41502518, 2025). "Meanwhile, the Beclin‐1‐derived peptides promoted autophagy in tumor cells, sensitizing them to heat‐induced damage." (PMID 40529859, 2025). "Beclin-1 is a key regulatory factor in the autophagy process, and research advancements regarding its role in the tumor immune microenvironment, immunotherapy, and drug sensitivity indicate its potential application value in cancer treatment." (PMID 39650649, 2024). "In our study, we aimed at studying BECN1 expression in tumor and adjacent normal tissues as well as correlation to clinicopathological features and disease-free survival after 2 years of follow up." (PMID 38787424, 2024). "Beclin-1 (BECN1) is a tumour suppressor that has been shown to increase autophagy by participating in the lysosomal degradation pathway." (PMID 39791706, 2024). "Stratifin promotes the assembly of the TRAF6-BECN1-VPS34 complex and enhances BECN1 ubiquitination, thereby facilitating tumor progression through autophagy induction." (PMID 38169510, 2024). "By combining Beclin-1 modulators with immunotherapeutic agents, it is possible to significantly improve anti-tumor immune responses." (PMID 39650649, 2024). "In NSCLC cells with sensitive EGFR mutations, EGFR kinase inhibitors can trigger autophagy by disrupting tyrosine phosphorylation of Beclin-1, leading to enhanced tumor growth and resistance to TKI treatment." (PMID 39650649, 2024). "In terms of drug sensitivity, Beclin-1 also plays an important role in the sensitivity of tumor cells to chemotherapy." (PMID 39650649, 2024). "We analyzed the expression of BECN1 in relation to GAPDH in both tumor tissues and their corresponding adjacent normal tissues." (PMID 38787424, 2024). "In the 1990s, Levine’s group identified BECN1 as a tumor suppressor, providing the first insight into autophagy’s role in cancer." (PMID 38933333, 2024). "While the status of BECN1 as a bona fide tumor suppressor remains under debate, its significant cellular role is undeniable." (PMID 39403142, 2024). "The activation of JNK dissociates the Bcl-2-Beclin-1 complex, which frees Beclin-1 from inhibition and activates autophagy to sustain the nutrient-deprived tumor cells." (PMID 38279220, 2024). "In the tumor immune microenvironment, Beclin-1 influences the interaction between tumor cells and immune cells by regulating autophagy." (PMID 39650649, 2024). "While its role as an autophagy inducer can explain some of the intrinsic functions of BECN1 in tumor progression, recent studies have also highlighted various autophagy-independent functions of BECN1." (PMID 38744820, 2024). "TMQ treatment also increased the protein expression of Bax, Caspase-3, and Beclin-1 in tumor tissues." (PMID 39508039, 2024). "During the progression of normal cervix to invasive cancer, the expression of key autophagy markers (LC3 and beclin-1) gradually decreases and is negatively correlated with tumor differentiation, lymph node metastasis, and patient prognosis." (PMID 39103348, 2024). "BECN1 protein (Beclin 1) is a crucial regulator of autophagic PCD, and the BECN1 gene acts as a tumor-suppressor haploinsufficient gene." (PMID 39641053, 2024). "The ratio of BECN1 expression in tumor tissue to adjacent normal tissue (BECN1 T/N ratio) for each case was calculated." (PMID 38787424, 2024). "Beclin-1 is also a tumor suppressor, and its expression level is negatively correlated with the activity of tumor cells." (PMID 38188151, 2024). "Beclin-1, an essential autophagy protein, suppresses tumor formation by removing defective or damaged organelles in healthy cells and supports tumorigenesis by stimulating cancer initiation and progression." (PMID 38596136, 2024).